HEMGN (hemogen)
Description:
Regulates the proliferation and differentiation of hematopoietic cells. Overexpression block the TPA-induced megakaryocytic differentiation in the K562 cell model. May also prevent cell apoptosis through the activation of the nuclear factor-kappa B (NF-kB).
Synonyms: EDAG-1; EDAG; NDR; CT155
Tractability: No criterion of Open Targets' tractability assessment is met for any kind of drug.
Gene: Protein-coding gene on chromosome 9 (97,926,791 to 97,944,856, reverse strand). Ensembl gene ENSG00000136929.
Subcellular location: Nucleus
Subcellular location (Human Protein Atlas): Nucleoplasm
Gene Ontology:
Molecular function: protein binding
Biological process: regulation of osteoblast differentiation; cell differentiation
Cellular component: nucleoplasm; nucleus
Genetic constraint (gnomAD): Loss-of-function variants: 25 observed, 37.07 expected, observed/expected ratio (o/e) 0.67, 90% interval 0.49 to 0.94. The upper end of that interval is the gene's LOEUF score, 0.94, which puts it in group 3 of 6, group 1 being the genes least tolerant of losing a copy. Missense variants: 448 observed, 506.35 expected, observed/expected ratio (o/e) 0.88, 90% interval 0.82 to 0.96. Synonymous variants: 153 observed, 159.95 expected, observed/expected ratio (o/e) 0.96, 90% interval 0.84 to 1.09.
Homologues: Orthologues: chimpanzee HEMGN (99% identical), macaque HEMGN (92% identical), dog HEMGN (65% identical), pig TRMO (61% identical), mouse Hemgn (46% identical), rat Hemgn (45% identical), mouse Hemgnl (31% identical).
Diseases named in the same sentence as HEMGN in open-access papers:
HEMGN is named in the same sentence as 13 diseases in open-access papers, as found by Europe PMC text mining. Sharing a sentence is not in itself a finding about the gene and the disease. The quoted sentences say what the papers report.
acute myeloid leukemia (2 papers, 2016 to 2022). Acute myeloid leukemia (AML) is a group of neoplasms arising from precursor cells committed to the myeloid cell-line differentiation. "High expression of HEMGN, a nucleoprotein involved in regulating the proliferation and differentiation of hematopoietic cells, reportedly indicates a better prognosis in acute myeloid leukemia." (PMID 35273597, 2022).
papillary thyroid carcinoma (2 papers, 2021 to 2023). "Of note, a recent study revealed an alternative way of HEMGN regulation in papillary thyroid carcinoma, where circ-PSD3 sponge miR-637 increases the levels of HEMGN, and activates PI3K/AKT signaling." (PMID 34205978, 2021).
thyroid carcinoma (2 papers, 2021 to 2023). "HEMGN, also known as EDAG-1 (Embryonic develop-associated gene 1) is upregulated in thyroid carcinoma tissues and cells, and it has been proposed to regulates the proliferation and apoptosis of cells via PI3K/Akt signaling pathway." (PMID 33903625, 2021). "HEMGN is upregulated in thyroid carcinoma tissues and cells and regulates cellular proliferation and apoptosis via the PI3K/Akt signalling pathway." (PMID 37760841, 2023).
anemia (1 paper, 2024). A reduction in the number of red blood cells, the amount of hemoglobin, and/or the volume of packed red blood cells. "Other relevant findings include the low overall expression of membrane genes and genes involved in erythropoiesis (GATA1, ALAS2, ABCB10, and HEMGN) in CSA and overexpression in the rest of the congenital anemias studied compared to healthy controls." (PMID 39519257, 2024).
diabetes (1 paper, 2022). "The free energy of the interaction of miR-466 and ID00436.3p-miR with mRNA of the BACH2, FASLG, HEMGN and IGF2R genes, which are involved in diabetes diseases, is −105 ± 1 kJ/mole with GU repeats in the 3′UTR." (PMID 35627185, 2022).
glioma (1 paper, 2022). A benign or malignant brain and spinal cord tumor that arises from glial cells (astrocytes, oligodendrocytes, ependymal cells). "These miR-637-targeted genes include HMGA1, CDK6, and WNT7A in glioma, HEMGN in PTC, APLN in GC, USP21 in HCC, LY6E and CTSB in CHOL, NUPR1 in OSCC and MM, HDAC4 in SaOS, ABL1 in CML, KLK4 in OC, PLXNB2 in OC, AKT1 in TNBC, PTC, and HCC, AKT3 in TNBC, and RING1 in CCa." (PMID 36175921, 2022). "Low expression of miR-637 leads to up-regulation of the expression levels of HEMGN in PTC, NUPR1 in OSCC, and AKT1 in glioma and PDAC, thereby activating the PI3K/AKT signaling pathway and inhibiting the reproduction and growth of cancer cells." (PMID 36175921, 2022). "These genes include HMGA1 in glioma, AKT1 in glioma, PTC, GC, and HCC, HEMGN in PTC, APLN and MMP19 in GC, WNT1 in CRC, NUPR1 in CRC and OSCC, LY6E and CTSB in CHOL, KLK4 and PLXNB2 in OC, and HDAC4 and STAT3 in SaOS." (PMID 36175921, 2022).
myelodysplastic syndrome (1 paper, 2024). A clonal hematopoietic disorder characterized by dysplasia and ineffective hematopoiesis in one or more of the hematopoietic cell lines. "This has been described in myelodysplastic syndrome (MDS) patients, where a low expression of HEMGN contributes to intranuclear delocalization of GATA1 and may contribute to the worsening of ineffective erythropoiesis." (PMID 39519257, 2024).
cancer (4 papers, 2019 to 2022). A tumor composed of atypical neoplastic, often pleomorphic cells that invade other tissues. "Circ-PSD3 limits the replicative potential of cancer cells and impedes apoptosis by regulating HEMGN." (PMID 36230649, 2022). "miR-637 blocks cancer cell cycle progression by targeting HEMGN and LIF." (PMID 36175921, 2022).
neoplasm (2 papers, 2016 to 2022). A benign or malignant tissue growth resulting from uncontrolled cell proliferation. "MS4A3 is a hematopoietic cell cycle regulator, and HEMGN plays an important role in hematopoietic development and neoplasms and is also involved in differentiation and proliferation." (PMID 27579896, 2016). "The HEMGN gene plays an important role in hematopoietic development and neoplasms and is also involved in differentiation and proliferation." (PMID 27579896, 2016).
HEMGN also shares sentences with these, for which no sentence is quoted: breast carcinoma (2 papers); triple-negative breast carcinoma (2); osteonecrosis (1); osteosarcoma (1).